DYSF (dysferlin)
Diseases named in the same sentence as DYSF in open-access papers (continued):
Sharing a sentence is not in itself a finding about the gene and the disease.
muscular dystrophy (continued). "In the present study, however, we showed that although (dysferlinsjl/+: fukutinHp/−) mice did not exhibit a muscular dystrophy phenotype, (dysferlinsjl/sjl: fukutinHp/−) mice developed a more exacerbated phenotype than did the dysferlin single-mutant (dysferlinsjl/sjl: fukutinHp/+) mice." (PMID 25198651, 2014). "However, dysferlin-deficient SJL and A/J mice have a progressive muscular dystrophy phenotype, suggesting that MG53 is necessary but not sufficient for efficient sarcolemmal repair." (PMID 23145354, 2012).
Miyoshi myopathy (90 papers, 2007 to 2025). A distal myopathy, characterized by weakness in the distal lower extremity posterior compartment (gastrocnemius and soleus muscles) and associated with difficulties in standing on tip toes. "While DYSF mutations commonly manifest as limb-girdle muscular dystrophy (LGMDR2) or distal Miyoshi myopathy, atypical manifestations, such as asymptomatic hyperCKemia and pseudometabolic myopathy, are rarely reported." (PMID 40545540, 2025). "Miyoshi myopathy is thought to occur due to genetic mutations in the DYSF gene, which codes for the dysferlin protein, which is critical for muscle cell membrane integrity and muscle fiber adhesiveness." (PMID 40786343, 2025). "Miyoshi myopathy (MM) is an autosomal recessive dysferlinopathy caused by a mutation in the dysferlin (DYSF) gene on chromosome 2p." (PMID 39376872, 2024). "Dysferlin is mutated in patients afflicted with Miyoshi myopathy and distal anterior compartment myopathy, as well as in LGMD2B." (PMID 36902136, 2023). "Mutations in the DysF domain of Dysferlin cause limb girdle muscular dystrophy type 2B2 and Miyoshi myopathy." (PMID 37409490, 2023). "Consistent with its role in membrane repair, mutations in the dysferlin gene are linked to two diseases characterized by muscle weakness, Miyoshi myopathy and LGMD type 2B (LGMD2B)." (PMID 36728029, 2023). "It has been reported that more than 140 mutations in the DYSF gene causing 2B and more than 100 mutations causing Miyoshi myopathy have been identified [DYSF gene (dysferlin), 2020]." (PMID 35273475, 2022). "Mutations in dysferlin (DYSF) present as Miyoshi muscular dystrophy (MIM 254130) and limb-girdle muscular dystrophy type 2B (MIM 253601)." (PMID 31413155, 2019). "The P731R mutation in dysferlin results in a similar clinical diagnosis to Miyoshi Myopathy, that of Limb-Girdle Muscular Dystrophy-Type 2B." (PMID 30026467, 2018). "Two mutations have been defined within the FerA domain of dysferlin that have been linked to either Miyoshi Myopathy (V705M) or Limb-Girdle Muscular dystrophy (P731R)." (PMID 30026467, 2018). "Both LGMD2B and a related disorder, Miyoshi Myopathy (MM) are caused by loss-of-function mutations in the Dysferlin gene product." (PMID 24244862, 2013). "Miyoshi myopathy (MM) is a congenital distal myopathy caused by defective muscle membrane repair as a result of mutations in DYSFERLIN." (PMID 23626698, 2013). "Mutations in the dysferlin gene are the cause of Limb-girdle Muscular Dystrophy type 2B and Miyoshi Myopathy." (PMID 22666441, 2012). "Miyoshi myopathy, a type of distal myopathy with predominant involvement of the posterior calf muscles, has been assigned to mutations in the dysferlin gene." (PMID 23050857, 2012). "The case presented in this report further strengthens the underlying genetic heterogeneity in Miyoshi myopathy-like phenotypes and adds another family to non-dysferlin, Miyoshi myopathy type 3 of late-onset." (PMID 23050857, 2012). "Mutations in dysferlin lead to limb girdle muscular dystrophy 2B, Miyoshi Myopathy and distal anterior compartment myopathy." (PMID 20405035, 2010). "The upregulation of DYSF (Dysferlin) has previously been shown to be associated with muscle weakness and irregular gait while mutations in this gene have been linked to various myopathies, including limb-girdle muscular dystrophy type 2B and Miyoshi myopathy." (PMID 40149400, 2025). "Dysferlin is mutated in Miyoshi myopathy and limb‐girdle muscular dystrophy." (PMID 33403800, 2021). "Mutations in DYSF lead to limb-girdle muscular dystrophy type 2B and Miyoshi myopathy." (PMID 29530068, 2018). "Loss of function mutations of the DYSF gene are an established disease mechanism in limb girdle muscular dystrophy (LGMD) and Miyoshi myopathy, although patients with DYSF mutations typically have a later onset and milder disease compared to the patients in our study." (PMID 25821721, 2015).
Miyoshi myopathy (continued). "Miyoshi myopathy (MM) is caused by autosomal recessive mutations in the human dysferlin gene." (PMID 23050857, 2012). "In comparison to dysferlin-deficient Miyoshi myopathy or Miyoshi distal myopathy type 1 (MMD1), MMD1 patients typically have more symmetrical involvement and a younger age of onset (usually before 30 years old)." (PMID 36292621, 2022). "Mutations in the DYSF gene may cause either LGMD2B or a Miyoshi myopathy phenotype." (PMID 36203997, 2022). "Mutated dysferlin leads to compromised membrane integrity and repair, resulting in the phenotypes associated with Miyoshi Myopathy (MM) and Limb-Girdle Muscular Dystrophy 2B (LGMD2B)." (PMID 34831431, 2021). "Dysferlin is best characterised in the developmental role of muscle myopathies, specifically limb girdle muscular dystrophy (LGMD), Miyoshi myopathy (MM) and distal anterior myopathy as a result of gene (DYSF) mutations." (PMID 31520263, 2019). "DYSF mutations lead to a wide range of muscular phenotypes, with the most prominent being Miyoshi myopathy (MM) and limb girdle muscular dystrophy type 2B (LGMD2B)." (PMID 23406536, 2013). "Miyoshi Myopathy (MM) is a congenital distal myopathy caused by defective muscle membrane repair due to mutations in DYSFERLIN." (PMID 23626698, 2013). "Dysferlin is a sarcolemmal protein, and dysferlin deficiency causes Miyoshi myopathy (MM) and limb girdle muscular dystrophy type 2B (LGMD2B)." (PMID 23145354, 2012). "Dysfunction of dysferlin is associated with limb–girdle muscular dystrophy 2B (LGMD2B) and Miyoshi myopathy." (PMID 40740503, 2025). "Dysferlin and myoferlin mutations cause muscle diseases: limb-girdle muscular dystrophy type 2B (LGMD2B), Miyoshi myopathy (Dysferlin), and muscular dystrophy with cardiomyopathy (Myoferlin)." (PMID 37538852, 2023). "Pathogenic variants in DYSF lead to abnormal muscle wasting and cause different clinical phenotypes mainly including limb-girdle muscular dystrophy type R2 (LGMD R2) and Miyoshi myopathy (MM)." (PMID 36319958, 2022). "DYSF mutations have been associated with several autosomal recessive inherited conditions: limb-girdle muscular dystrophy type 2B (LGMD2B), Miyoshi myopathy (MM), asymptomatic hyperCKemia, and distal myopathy with anterior tibial onset (DMAT)." (PMID 36042458, 2022). "Mutations in the DYSF gene, encoding dysferlin, are responsible for Limb Girdle Muscular Dystrophy type R2/2B (LGMDR2/2B), Miyoshi myopathy (MM), and Distal Myopathy with Anterior Tibialis onset (MDAT)." (PMID 36012197, 2022). "While the absence of dysferlin is known to lead to skeletal muscle damage in limb girdle muscular dystrophy type 2B and Miyoshi myopathy, the effects of dysferlin in the heart are less well known." (PMID 32839504, 2020). "Various DYSF allelic variants are pathogenic, resulting in the LOF conditions Miyoshi muscular dystrophy 1 and limb-girdle muscular dystrophy type 2B, where patients experience progressive muscle weakness and atrophy." (PMID 31649251, 2019). "Eventhough DYSF pathogenic variants are mainly associated with LGMD2B and Miyoshi myopathy, subtle cardiac dysfunction have also been described in patients with DYSF mutations, and supported by a number of experimental studies." (PMID 31297131, 2019). "The dysferlin mutations were involved in Limb-Girdle muscular dystrophy 2B (LGMD2B), a autosomal recessive degenerative myopathy, and in Miyoshi muscular dystrophy 1 (MMD1), a late-onset muscular dystrophy." (PMID 31443490, 2019). "Dysferlin mutations cause a number of different phenotypes including limb girdle muscle dystrophy type 2B (LGMD2B), Miyoshi distal myopathy (MM) and distal myopathy with Anterior Tibialis onset (DMAT)." (PMID 27666772, 2016). "Dysferlin is reduced in patients with limb girdle muscular dystrophy type 2B, Miyoshi myopathy, distal anterior compartment myopathy, and in certain Ethnic clusters." (PMID 26444858, 2015).
Miyoshi myopathy (continued). "In humans, dysferlin deficiency leads to LGMD2B, Miyoshi myopathy or a distal myopathy with anterior tibial onset." (PMID 25198651, 2014). "Three clinically distinct autosomal recessive muscular dystrophies are attributed to DYSF mutations: limb-girdle muscular dystrophy type 2B (LGMD2B), Miyoshi myopathy (MM), and distal myopathy with anterior tibial onset (DMAT)." (PMID 25562650, 2013). "The majority of our understanding of mammalian ferlin proteins has come from studies focusing on dysferlin, as mutations in the dysferlin gene lead to limb girdle muscular dystrophy type 2B (LGMD2B) and Miyoshi myopathy." (PMID 22808170, 2012). "Two ERAD models were also recently proposed for disposal of dysferlin, a type-II transmembrane protein involved in muscular dystrophy type 2B and Miyoshi myopathy." (PMID 22461906, 2012). "Mutations in dysferlin cause limb girdle muscular dystrophy 2B (LGMD2B), Miyoshi Myopathy (MM) and distal anterior compartment myopathy." (PMID 20405035, 2010). "Moreover, MaxCyte enabled predominantly homozygous knockin efficiencies in as many as 72% of subclones at the DYSF gene locus in Miyoshi myopathy patient iPSCs." (PMID 33711268, 2021). "The loss of the protein dysferlin due to mutations in the DYSF genes results in defective muscle membrane repair leading to muscle breakdown, which is the basis of either limb-girdle muscular dystrophy type 2b (LGMD2B) or Miyoshi myopathy." (PMID 34451881, 2021). "Interestingly, we found the same compound heterozygous mutations in the DYSF gene in siblings with discordant phenotypes (LGMD in the sister, Miyoshi myopathy in the brother)." (PMID 29970176, 2018). "Specific muscle groups could be targeted by intramuscular delivery for dysferlin phenotypes that include Miyoshi myopathy and distal anterior compartment myopathy." (PMID 22720081, 2012). "Mutations in the human DYSF gene cause myopathies, including limb–girdle muscular dystrophy type 2B (LGMD2B), Miyoshi myopathy (MM), and distal anterior compartment myopathy." (PMID 35454077, 2022). "DYSF gene is involved in limb-girdle muscular dystrophy type 2B (LGMD2B), \LGMDR2, Miyoshi myopathy disease type 1 (MMD1), and a rare form of distal anterior compartment myopathy (DACM)." (PMID 35273475, 2022). "DYSF defects can result in different forms of neuromuscular disorders such as Miyoshi myopathy (MM), limb-girdle muscular dystrophy type R2 and Distal myopathy (DM)." (PMID 33330280, 2020). "Mutations in Dysferlin give rise to limb-girdle muscular dystrophy type 2B (LGMD2B) and Miyoshi myopathy (MM), as well as distal myopathy with onset in the tibialis anterior muscles." (PMID 26798425, 2016). "Among them, LGMD-2B and Miyoshi myopathy (MM) develop due to defects in the dysferlin gene, coding for a membrane protein mainly required for vesicle traffic and membrane repair." (PMID 25028653, 2014). "Dysferlin has been linked to Limb Girdle Muscular Dystrophy type R2 (LGMD R2), which encompasses several phenotypes previously referred to as Miyoshi myopathy (MMD1), LGMD 2B, distal myopathy of the anterior tibialis (DMAT), and asymptomatic hyperCKemia." (PMID 41227369, 2025). "Conditions with distinct phenotypic presentations that have been associated with DYSF gene mutations include limb-girdle muscular dystrophy type 2B (LGMD2B), Miyoshi myopathy (MM), asymptomatic hyperCKemia, and distal myopathy with anterior tibial onset (DMAT)." (PMID 36042458, 2022). "Blunted dysferlin expression results in limb-girdle muscular dystrophy type 2B (LGMD2B) and Miyoshi myopathy, which leads to progressive muscle weakness in humans and rodents, and highlights an important role of dysferlin in skeletal muscle homeostasis." (PMID 34366880, 2021). "Defects in the DYSF gene result in several types of muscular dystrophy; including limb-girdle muscular dystrophy type 2B (LGMD2B), Distal Myopathy (DM), and Miyoshi myopathy (MM)." (PMID 33228026, 2020).
Miyoshi myopathy (continued). "Mutations in dysferlin have been shown to lead to a variety of muscle phenotypes that range from mild to severe, including the prominent Limb-Girdle Muscular Dystrophy type 2B [LGMD2B; OMIM 253601;] and Miyoshi Myopathy (MM, OMIM 254130,]." (PMID 22666441, 2012). "Dysferlin is the product of the gene responsible for LGMD2B, Miyoshi myopathy and distal anterior compartment myopathy." (PMID 21798100, 2011). "There are more than 260 polymorphic mutations in DYSF reported to result in three types of muscular dystrophies: limb-girdle autosomal recessive muscular dystrophy type 2B (LGMDR or LGMD2B), Miyoshi myopathy (MM), and distal myopathy with anterior tibial onset (DMAT)." (PMID 37892218, 2023). "In contrast LGMD2B and Miyoshi myopathy patients typically show complete or partial absence of the dysferlin band on immunoblot of skeletal muscle or blood monocytes." (PMID 21798100, 2011). "Dysferlin is an integral membrane protein of skeletal muscle that is missing in individuals with Limb Girdle Type 2B (LGMD2B), Miyoshi Myopathy (MMD1) and other, rarer muscular dystrophies." (PMID 36406982, 2022).
limb-girdle muscular dystrophy type 2B (44 papers, 2007 to 2026). "Limb-girdle muscular dystrophy type 2B (LGMD2B) is a degenerative muscle disorder induced by mutations in the dysferlin gene." (PMID 41517735, 2026). "Mutations in DYSF cause limb-girdle muscular dystrophy type 2B (LGMD2B) due to defective Ca2+-dependent, vesicle-mediated membrane repair." (PMID 34466782, 2021). "The same mutation in the DYSFERLIN gene was found in another muscular dystrophy: limb-girdle muscular dystrophy type 2B (LGMD2B)." (PMID 32854405, 2020). "In humans, mutations in the DYSF gene give rise to limb-girdle muscular dystrophy type 2B (LGMD2B), Miyoshi myopathy or distal myopathy with anterior tibialis onset." (PMID 30092031, 2018). "Defective expression of dysferlin, a ubiquitously expressed 230-kDa transmembrane protein that has been shown to be involved in resealing muscle fiber membranes, causes limb-girdle muscular dystrophy type 2B (LGMD2B) or Miyoshi-myopathy in humans." (PMID 21533183, 2011). "Mutations of dysferlin (Dysf), a key sarcolemma integrity protein, lead to dysferlinopathies including limb-girdle muscular dystrophy type 2B (LGMD2B) due to impaired calcium-dependent fusion of lipid patches and transmembrane protein trafficking during sarcolemma resealing after mechanical injury." (PMID 39138561, 2024). "As a critical component of a membrane repair complex, dysferlin is hypothesized to orchestrate sealing of membrane defects in muscles, with dysferlin mutation and consequent dysfunction giving rise to limb girdle muscular dystrophy type 2B (also called LGMD R2 dysferlin-related)." (PMID 36902136, 2023). "Although there are no existing animal models that mimic Carey-Fineman-Ziter syndrome resulting from MYMK mutations, mutations in DYSF, the gene responsible for heterogenous limb-girdle muscular dystrophy type 2B (LGMD2B), results in myoblast fusion deficiency." (PMID 36400788, 2022). "Quantitative surface plasmon resonance (SPR) was utilized to determine binding strength and calcium dependence of direct interactions between dysferlin and proteins likely to mediate skeletal muscle repair, interrupted in limb girdle muscular dystrophy type 2B/R2." (PMID 36902136, 2023). "Finally, we showed that the dystrophic features of the Dysferlin-null mice, a model of limb-girdle muscular dystrophy type 2B, were reversed when expressing ELMO2 in an open conformation." (PMID 36400788, 2022). "Limb-girdle muscular dystrophy type 2B (LGMD2B) is caused by mutations in the dysferlin gene, resulting in non-functional dysferlin, a key protein found in muscle membrane." (PMID 32881965, 2020).
limb-girdle muscular dystrophy (24 papers, 2011 to 2025). Limb-girdle muscular dystrophy (LGMD) is a heterogeneous group of muscular dystrophies characterized by proximal weakness affecting the pelvic and shoulder girdles. "Dysferlin plays a key role in cell membrane repair; its absence or malfunction in patients with dysferlin‐deficient limb girdle muscular dystrophy leads to muscle fibre death." (PMID 39900102, 2025). "In addition, P-188 NF was shown to prevent muscle atrophy in the dysferlin-deficient SJL mouse model of limb-girdle muscular dystrophy using the s.c. route of delivery at an effective daily dose of approximately 16 mg/Kg." (PMID 26248188, 2015). "Limb-girdle muscular dystrophy (LGMD) is a progressive muscle weakness affecting the pelvic and shoulder girdles, primarily caused by mutations in proteins like myotilin, lamin, caveolin-3, calpain-3, dysferlin, γ-sarcoglycan, TCAP, TRIM32, FKRP, and titin." (PMID 39415830, 2024). "On identifying the relevant variants in the CAPN3, DYSF, and TCAP genes, the diagnosis was oriented toward limb-girdle muscular dystrophy (LGMD) in six patients from four families." (PMID 37377599, 2023). "Previous research has shown that late-onset muscular dystrophies, such as limb-girdle muscular dystrophy (LGMD) type 2B/R2, are associated with mutations in the DYSF gene and that persistent alterations in serum CK levels can serve as early markers of these degenerative muscle processes." (PMID 39595661, 2024). "For example, mutations in muscle specific genes such as the calcium sensing sarcolemma protein Dysferlin and the endocytosis required protein caveolin-3, which lead to different human limb girdle muscular dystrophies (LGMD2B and LGMD1C, respectively), are required for cellular wound healing." (PMID 36139352, 2022). "Therefore, additional therapeutic options should be taken into consideration to address limb-girdle muscular dystrophy, including dysferlin restoration." (PMID 32560255, 2020). "For these individuals, mutation analysis was extended to include the seven most common limb-girdle muscular dystrophy (LGMD) genes (DYSF, CAPN3, SGCA, SGCB, SGCC, SGCD, and FKRP)." (PMID 31588416, 2017). "The SJL stain develops spontaneous myopathy due to a splice-site mutation in the Dysferlin (Dysf) gene which results in decreased levels of dysferlin protein and this makes the SJL stain a good model for limb girdle muscular dystrophy." (PMID 30395621, 2018). "In the subjects with CK ≥ 2000 U/l without DMD mutations, the most common limb-girdle muscular dystrophy (LGMD) genes were investigated and mutations in DYSF, SGCB and FKRP genes were found." (PMID 32112218, 2020). "Limb-girdle muscular dystrophy (LGMD) describes a group of disorders primarily affecting the shoulder and pelvic girdle muscles, which have both autosomal dominant and recessive inheritance, and involve a variety of proteins including sarcoglycans, dysferlin, and caveolin." (PMID 21798096, 2011).